TNF (tumor necrosis factor)
Diseases named in the same sentence as TNF in open-access papers (continued):
Sharing a sentence is not in itself a finding about the gene and the disease.
inflammatory bowel disease (continued). "Indeed, in an experimental model of inflammatory bowel disease, CBG reduced IL-1β and IFN-γ levels in inflamed colons, while in a model of Huntington’s disease, CBG was able to decrease the expression of TNF-α and interleukin 6 (IL-6)." (PMID 29986533, 2018). "In inflammatory bowel disease, CXCL10 likely leads to intestinal barrier damage by virtue of its abundance and capability to stimulate myeloid-derived cells to produce tissue-damaging cytokines, such as IL-12, IL-23, and TNF-α." (PMID 29910805, 2018). "TNF-α-neutralizing antibodies, such as infliximab (IFX) and adalimumab (ADA), are effective in the treatment of inflammatory bowel diseases (IBD), but they are expensive and become ineffective when patients develop anti-IFX or anti-ADA antibodies (ATI and ATA, respectively)." (PMID 30533022, 2018). "The authors stated that direct exposure to anti-TNFα therapy did not result in increased adverse pregnancy outcomes, but it was worse, compared to pregnancies before inflammatory bowel disease diagnosis." (PMID 28044081, 2016). "Recently, infliximab, the chimeric anti-human tumor necrosis factor alpha (TNF-α) antibody, has been largely applied for the treatment of inflammatory bowel disease (IBD), and a few reports have shown its partial effectiveness in the management of rectovaginal fistulas associated with UC." (PMID 25368705, 2014). "Although anti-TNF-α strategies have proved beneficial in other clinical settings such as inflammatory bowel disease, there are no clinical trials of anti-TNF-α agents in stroke." (PMID 23431245, 2013). "Although anti-TNF-α strategies have proved beneficial in other clinical settings such as inflammatory bowel disease, there have been no clinical trials of anti-TNF-α agents in stroke." (PMID 23326018, 2012). "Research has confirmed that pro-inflammatory cytokines such as IL-1β, TNF-α, IL-18, along withsignaling molecules like MyD88 and NF-κB, play central roles in regulating inflammatory responses and have been established as core biomarkers in DSS-induced inflammatory bowel disease (IBD) models." (PMID 41227621, 2025). "Interestingly, in patients with inflammatory bowel disease and anti-TNF-α therapy the increase in Th17 and IL-17A levels indicates a better outcome, while the opposite is observed in MS patients, who worsen as IL-17 increases under TNF-α blockade." (PMID 41142785, 2025). "Additionally, KEGG analysis demonstrated that the DEGs were predominantly enriched in pathways such as the TNF signaling pathway, IL-17 signaling pathway, FOXO signaling pathway, inflammatory bowel disease (IBD), HIF-1 signaling pathway, and intestinal immune network for IgA production." (PMID 40303487, 2025). "In inflammatory bowel disease (IBD), they may be utilized in conjunction with biologics, such as monoclonal antibodies, to achieve deeper remission; for instance, microbial therapy could maintain mucosal repair between anti-TNF medication infusions." (PMID 40767874, 2025). "In a study on inflammatory bowel disease, CD8αβ+ γδ T cells were shown to display a cytotoxic type 1 effector profile, including the production of IFN-γ, were inversely correlated with the degree of disease activity and were restored to normal levels upon anti-tumor necrosis factor (TNF) therapy." (PMID 38802512, 2024). "Long-term fasting decreased intestinal permeability and the concentration of pro-inflammatory cytokines such as the tumor necrosis factor (TNF)-α, both of which are involved in inflammatory bowel disease (IBD)." (PMID 39599741, 2024). "The superpathway of L-cysteine biosynthesis (mammalian) can produce L-cysteine to downregulate the production of pro-inflammatory cytokines like IL-6, TNF-α, interferon-γ (IFN-γ), and IL-1β in inflammatory bowel disease (IBD)." (PMID 38675747, 2024).
inflammatory bowel disease (continued). "Furthermore, treatment of inflammatory bowel disease (IBD)-induced mice with compound 1 decreased myeloperoxidase activity in colonic extracts and modulated the colon length and serum levels of cytokines such as TNF–α, IFN–γ, IL–6, IL–1β, and IL–10." (PMID 37893090, 2023). "- The choice of first-line biological treatment in axial forms (anti-TNF or anti-IL17, generally anti-TNF) must take into account the presence or absence of uveitis or Inflammatory bowel disease (IBD), patient’s profile, and the decision must be shared between the patient and the physician." (PMID 37654637, 2023). "Genes classified in the pathway analysis were heavily involved in the TNF signaling pathway, Jak-STAT signaling pathway, PI3K-Akt signaling pathway, cancer-related pathways, inflammatory bowel disease (IBD) and so on." (PMID 36982944, 2023). "However, in cases of inflammatory bowel disease and celiac disease, IL-15 production is increased, leading to the recruitment and activation of inflammatory and innate immune cells and the production of IFN-γ and TNF-α." (PMID 38140264, 2023). "Infliximab belongs to the family of tumor necrosis factor (TNF) alpha inhibitors and since its development, it has revolutionized treatment for both rheumatological diseases and inflammatory bowel disease (IBD)." (PMID 36721597, 2022). "Next, we tested the function of TNFα- and IFNγ-licensed MSCs by employing dextran sulfate sodium (DSS)-induced inflammatory bowel diseases (IBD) model in C57BL/6 J mice." (PMID 36195887, 2022). "Interestingly, high levels of circulating OSM have repeatedly been reported in patients with inflammatory bowel disease that does not respond to TNF inhibitors." (PMID 36124688, 2022). "Moreover, a meaningful correlation was observed between proinflammatory cytokines such as TNF and IL-2 concentration in the poor prognosis of the disease among the patients with pre-existing gut-related health conditions such as inflammatory bowel disease (IBD)." (PMID 34066983, 2021). "AU and inflammatory bowel disease (IBD) history were less frequent in the ETN and anti-IL17A groups than in the anti-TNF mAb." (PMID 34271991, 2021). "Another set of extracted data from the Pregnancy in Inflammatory Bowel Disease and Neonatal Outcomes registry (PIANO) registry was published in 2018 reporting infant serologic responses to HiB and tetanus vaccines after antenatal exposure to biologics including anti-TNFα and ustekinumab." (PMID 34122062, 2021). "The substance class of tumor necrosis factor (TNF) inhibitors represents an established and effective option in the therapeutic algorithm of treating inflammatory bowel disease (IBD) patients." (PMID 34616488, 2021). "Patients with inflammatory bowel diseases (IBD) may be at higher risk of HEV infection due to a disturbed intestinal barrier function and immunosuppressive medications, such as glucocorticosteroids, thiopurines, and anti-tumor necrosis factor (TNF) agents or other biologicals." (PMID 33027305, 2020). "Furthermore, high levels of cleaved IgG were detected in serum from individuals with inflammatory bowel diseases, who did not respond to anti-TNFα TmAbs." (PMID 32117299, 2020). "However, 10%–40% of patients with inflammatory bowel disease failed to benefit from anti‐TNF therapy or lost response during use." (PMID 31958884, 2020). "In human patients with inflammatory bowel disease (IBD), DUSP22 expression was inversely correlated with disease activity and with the levels of IL-17 and TNF in the inflamed mucosa." (PMID 31159473, 2019). "Inflammatory bowel disease (IBD) is characterized by an imbalanced immune response, leading to a pro-inflammatory phenotype with elevated tissue concentrations of various cytokines including tumor necrosis factor (TNF), interleukin-6 (IL-6), and interferon-γ (IFNγ)." (PMID 31572379, 2019).
inflammatory bowel disease (continued). "Infliximab (IFX) is an intravenously administered monoclonal antibody antagonizing the effects of tumor necrosis factor-alpha (TNF) systemically and is efficacious in the treatment of inflammatory bowel disease (IBD)." (PMID 31450748, 2019). "Evidence arising from experimental models of inflammatory bowel disease suggests that CD4+ T cells are key players in the initiation and regulation of the immunopathologic processes, partly through production of proinflammatory cytokines such as tumor necrosis factor-α (TNF-α)." (PMID 30483153, 2018). "Infliximab (IFX, Remicade®) is a chimeric monoclonal IgG1 antibody against tumor necrosis factor (TNF), a central cytokine in inflammatory bowel disease (IBD)." (PMID 28272355, 2017). "Inflammatory bowel disease (IBD), comprised of Crohn’s disease and Ulcerative colitis, is a chronic inflammatory bowel disease with sustained up-regulation of inflammatory mediators such as TNF-α, IL-6, and IL-1, which themselves are regulated by the activation of NF-κB." (PMID 26205050, 2015). "Biologic therapy to inhibit tumor necrosis factor-alpha (TNF-α), a proinflammatory cytokine, has become a widely used, safe, and effective treatment for patients with inflammatory bowel disease (IBD)." (PMID 24707412, 2014). "In addition to this, there is evidence that patients with IBS-D have an increased expression of TNFα and IL-1β in the peripheral blood monocytes, not dissimilar to that found in patients with inflammatory bowel disease." (PMID 23651739, 2013). "In the context of inflammatory bowel disease (IBD), ASX supplementation has been shown to reduce colonic inflammation by downregulating cytokines such as TNF-α, IL-1β, and IL-6, while enhancing endogenous antioxidant defenses including superoxide dismutase and glutathione peroxidase." (PMID 40559644, 2025). "Besides, the increased production of IL-1, IL-6, IL-8, TNF-α and TGF-β in the jejunum were detected, indicating that AHBZ2303 or AHBZ2304 infection could induce host inflammatory response and contribute to inflammatory bowel disease, accompanied by significant pathological damage." (PMID 40290474, 2025). "The tumor necrosis factor inhibitor (TNFi) infliximab (IFX) and the α4/β7 integrin blocker vedolizumab (VDZ) are recommended first-line biologic treatments for patients with moderately to severely active inflammatory bowel disease (IBD)." (PMID 40648793, 2025). "Background/Objectives: The introduction of anti-tumor necrosis factor-α (anti-TNF-α) agents, particularly infliximab (IFX) and adalimumab (ADA), has significantly expanded the therapeutic arsenal for inflammatory bowel disease (IBD)." (PMID 39861147, 2025). "However, in individuals with inflammatory bowel disease, type 2 diabetes, and coronary artery disease serum Metrnl levels showed a significant negative correlation with serum inflammatory cytokines (TNF-α, IL-6)." (PMID 39964474, 2025). "HDACi treatment might improve the outcome of autoimmune and autoinflammatory-like inflammatory bowel disease (IBD) or RA through the induction of FLS growth arrest, anti-angiogenic properties, or suppression of pro-inflammatory cytokines like IL-6 and TNF-α." (PMID 39846569, 2025). "The agonist INT-747, a Farnesoid X receptor agonist, significantly reduces TNF-α secretion in activated human peripheral blood monocytes, purified CD14 monocytes and DCs, and monocytes from the lamina propria of inflammatory bowel disease (IBD) patients." (PMID 38903520, 2024). "In the inflammatory bowel disease (IBD) induced by LPS in human colon mucosal epithelial cells (NCM460), Mor reduced apoptosis, inflammation, and oxidative stress by regulating Bax/Bcl-2, inhibiting TNF-α, IL-1β, IL-6, SOD, MDA, T-AOC, and MPO levels." (PMID 39301568, 2024).
inflammatory bowel disease (continued). "While biologic therapies targeting tumor necrosis factor-alpha (anti-TNFα) are the current mainstay in both inflammatory bowel disease (IBD) and various autoimmune conditions, there is no “gold standard” for the assessment of anti-TNFα therapeutic efficacy." (PMID 38382470, 2024). "The parallel increase in inflammation marker TNF-α, along with AmotL2 expression in EGCs, varying from low TNF-α/medium AmotL2 signal in controls to high TNF-α/high AmotL2 after treatment, are interesting evidence that might indicate the involvement of EGCs in inflammatory bowel disease." (PMID 39335466, 2024). "Anti-TNF pharmacogenetic studies, including the different anti-TNF drugs infliximab (IFX), adalimumab (ADA) and etanercept (ETN), have so far been performed in RA, inflammatory bowel disease (IBD), PA and ankylosing spondylitis (AS) patients." (PMID 36833379, 2023). "The availability of anti-tumor necrosis factor-α (TNF-α) monoclonal antibodies such as infliximab (IFX) has significantly improved the outcome of Crohn’s disease (CD), an inflammatory bowel disease (IBD) that destroys gastrointestinal tissue." (PMID 37896168, 2023). "Enhanced IgG galactosylation has also been reported in patients with inflammatory bowel disease (IBD), CD and UC, treated with AZA/6MP compared to anti-TNFα Ig treatment, and in CD patients after VDZ implementation, while anti-TNFα therapy in CD resulted in the lower IgG agalactosylation." (PMID 37575234, 2023). "Thus, we evaluated the in vivo effects of RI-962 in two animal models of inflammatory diseases: TNFα-induced systemic inflammatory response syndrome (SIRS) and dextran sulfate sodium (DSS)-induced inflammatory bowel disease (IBD)." (PMID 36371441, 2022). "Despite the considerable efficacy of anti-Tumor Necrosis Factor (TNF)-α monoclonal antibody (mAb) therapy in the treatment of inflammatory bowel disease (IBD), about one third of patients do not respond." (PMID 33790898, 2021). "Thus, mono-antibodies of anti-TNF, such as adamumab (HUMIRA®) and infliximab (REMICADE®), are used for treatment of inflammatory bowel disease (IBD)." (PMID 32411291, 2020). "The aim of this study was to investigate the effect of anti-TNF therapy on glucose and lipid metabolism in nondiabetic, nonobese patients with inflammatory bowel disease (IBD)." (PMID 29576769, 2018). "Also, administration of an IL-23 plasmid to IL-12p40−/− mice up-regulates production of IFN-γ in response to Mycobacterium tuberculosis and IL-23 promotes IFN-γ production, rather than IL-17 production, via an IL-23– and TNF-α–dependent pathway in human inflammatory bowel disease." (PMID 24040208, 2013). "An analysis of TNFɑ-inhibitor-treated patients with inflammatory bowel disease (IBD) in the French National Health Insurance database also showed a higher rate of lymphoma (HR 2.41, 95% CI 1.60–3.64) compared with patients with IBD who had no TNF inhibitor exposure." (PMID 37554981, 2023). "Although we showed an acceptable rate of seroconversion among patients using anti-TNF therapy, reports show a persistent reduction in the titers of anti-SARS-CoV-2 spike protein antibody with time in patients with inflammatory bowel disease (IBD) who are on anti-TNF treatments." (PMID 35941646, 2022). "However, approximately 30% of patients with inflammatory bowel disease (IBD) fail to respond to anti-TNF, this condition is often known as primary non-response (PNR) (when a patient does not respond to an induction regimen of the biological agent)." (PMID 34079458, 2021). "This becomes even more concerning in RA and inflammatory bowel disease (IBD) patients who are on anti-TNF-α therapy despite the fact that it is not clear how anti- TNF-α therapy may dysregulate ACE2 expression and shedding." (PMID 34025650, 2021).
inflammatory bowel disease (continued). "In children with endoscopically and histologically confirmed non-inflammatory bowel disease and non-infectious pediatric idiopathic colitis, the presence of TGF-β, NaPo, and IL-1β or TNF-α promoted TC2 differentiation in vitro." (PMID 29922282, 2018). "The inflammation and inflammatory bowel disease (IBD) disorders had many commonly modulated genes that were also found in the String analysis that were common with the disorders which included IL-8, ICAM1, RELB, NFκBIA, TNFAIP3, LIF, CXCL1, CXCL2, CXCL3, CXCL10, and TNF-α." (PMID 28099447, 2017). "Considering the risk of reactivation of latent tuberculosis infection (LTBI), not only before starting tumor necrosis factor inhibitors but also before non-TNF inhibitor therapy, LTBI screening is routinely recommended for patients with inflammatory bowel disease (IBD)." (PMID 34095175, 2021).